NOTCH3 (notch receptor 3)
Diseases named in the same sentence as NOTCH3 in open-access papers (continued):
Sharing a sentence is not in itself a finding about the gene and the disease.
glioma (continued). "Our finding of high frequency NOTCH3 gain in glioma without significant alteration of other NOTCH members is novel and suggests that these alterations may be early and major events in gliomagenesis." (PMID 24143218, 2013). "The role of NOTCH3 in glioma invasion, adhesion and diffusion was not previously known." (PMID 24143218, 2013). "Thus, for the first time our studies show that NOTCH3 signaling promotes both migratory and invasive abilities of glioma cells and that its function is not limited only to stem cells development and proliferation." (PMID 24143218, 2013). "Considering both TRPM7 and Notch signaling function as oncogenes in glioma formation, it is not surprising to see that U87MG cells, transfected with M7-wt, express increased levels of Notch1 NICD, Notch2 NICD, and Notch3 NICD." (PMID 33381038, 2020).
vascular dementia (29 papers, 2012 to 2026). A degenerative vascular disorder affecting the brain. "NOTCH3 signalling is primarily limited to the VSMCs and as such mutations in NOTCH3 cause a gradual degeneration of these cells leading to recurrent infarcts and gradual development of vascular dementia." (PMID 36175824, 2022). "This is the first systematic study of NOTCH3 variants in a large Chinese cohort of Alzheimer's disease (AD) and subcortical vascular dementia (SVaD)." (PMID 33942994, 2021). "For example, cerebral autosomal dominant arteriopathy with subcortical infarcts and leukoencephalopathy (CADASIL), a typical inherited systemic arterial vessel disease that causes vascular dementia and lacunar infarction, is caused by mutations in the NOTCH3 gene in an autosomal dominant manner." (PMID 38255218, 2024). "NOTCH3 variants were associated with incident ischemic stroke and vascular dementia." (PMID 36300346, 2022). "We demonstrated that NOTCH3 and HTRA1 variants were associated with increased risk of ischemic stroke and vascular dementia." (PMID 36300346, 2022). "Each NOTCH receptor plays a different role in physiological processes; Relevant to CSVD, NOTCH3 mutations are the critical causative gene defect in CADASIL, which is an autosomal dominant stroke disorder that results in vascular dementia and is the most frequently inherited type of CSVD." (PMID 31811815, 2019).
pulmonary arterial hypertension (26 papers, 2012 to 2026). "Notch3 (neurogenic locus notch homolog protein 3) is implicated in vascular diseases, including pulmonary hypertension (PH)/pulmonary arterial hypertension." (PMID 37254738, 2023). "In contrast, another study demonstrated that pulmonary arterial hypertension associates with increased expression of NOTCH3 in whole lung, and that this was critical for the proliferative vasculopathy that is unique for pulmonary arterial hypertension." (PMID 28465505, 2017). "Notch3 expression is associated with the progression of pulmonary hypertension." (PMID 40453665, 2025). "Studies conducted at various time points during hypoxia-induced (in mice) or methylene blue-induced (in rats) pulmonary hypertension models showed an increase in Notch3 expression in the lungs as a function of time and disease severity." (PMID 40453665, 2025). "pulmonary artery smooth muscle cells from patients with pulmonary arterial hypertension recapitulated Notch3/Hes5 signaling, ER stress and redox changes observed in PH mice." (PMID 37254738, 2023). "Abnormal Notch3 signalling plays an important role in vascular remodelling, a hallmark of several cardiovascular diseases, including pulmonary arterial hypertension (PAH)." (PMID 31868216, 2019). "Notch3 has also been shown to play crucial roles in the human pulmonary arterial remodelling and pulmonary hypertension." (PMID 28266128, 2017). "Activation of the Notch3 cascade is involved in the development of pulmonary arterial hypertension by stimulating the proliferation of vascular smooth muscle cells." (PMID 26380809, 2015). "In pulmonary arterial hypertension, hypoxia upregulates Notch3 expression; Notch3 upregulation is a key initiating event of the disease." (PMID 23531541, 2013). "A protein biomarker, the NOTCH3 extracellular domain, identifies individuals with idiopathic pulmonary hypertension, correlates with disease progression, improves mortality risk prediction and provides a readily implementable, noninvasive blood test for this disease." (PMID 41514036, 2026). "Thus, hypoxia‐induced proliferation of vascular smooth muscle cells, known to be of critical importance in the progression of pulmonary arterial hypertension, was favoured in response to Notch3 signalling." (PMID 35611804, 2022). "Hypoxia has also been found to up-regulate Notch3 in lung tissue, alluding to the hypothesis of Notch3 serving as a potential therapeutic target to reduce pulmonary arterial hypertension." (PMID 33912195, 2021). "NOTCH3 is an important mediator of pulmonary artery remodeling in pulmonary arterial hypertension (PAH) that mediates the excessive proliferation and dedifferentiation of VSMCs329." (PMID 35332121, 2022). "For example, glycosylation is also required for Notch processing and trafficking, and changes in Notch3 signaling have been proposed to play a critical role in VSMC differentiation and the pathogenesis of pulmonary arterial hypertension." (PMID 34929167, 2022). "Gamma-secretase-mediated Notch3 signaling is involved in smooth muscle cell (SMC) hyper-activity and proliferation leading to pulmonary arterial hypertension (PAH)." (PMID 26367462, 2015). "The research found that, compared to animals in 21% oxygen, mice exposed to 6 weeks of hypoxia had three times higher levels of Notch3 expression at both the mRNA and protein (ICD) levels in their lungs, with pulmonary artery pressures consistent with late-stage pulmonary hypertension." (PMID 40453665, 2025). "After exposure to chronic hypoxia, Notch3+/+ mice developed excessive small pulmonary artery muscularization and luminal narrowing, consistent with advanced pulmonary hypertension, whereas Notch3−/− mice had normal-appearing small arteries without muscular thickening." (PMID 38892440, 2024).
pulmonary arterial hypertension (continued). "Given the importance of Notch3 in the regulation of VSMC function, it is not surprising that abnormal Notch3 signalling has been implicated in cardiovascular diseases associated with excessive VSMCs proliferation and vascular remodelling, including pulmonary arterial hypertension (PAH)." (PMID 31868216, 2019). "Earlier report suggested that Notch3 was upregulated in PH patients and in hypoxia- or MCT-induced rodent model of PH and, mice with homozygous deletion of Notch3 did not develop pulmonary hypertension in response to hypoxic stimulation." (PMID 25412097, 2014). "Indeed, in mouse and rat models, it has been demonstrated that treatment of pulmonary hypertension with an anti‐NOTCH3 antibody (Ab 28 042), which specifically binds to NOTCH3 and inhibits JAGGED1‐induced NOTCH3 cleavage, has no evident toxic side effects." (PMID 40354086, 2025).
hepatocellular carcinoma (25 papers, 2011 to 2026). A malignant tumor that arises from hepatocytes. "For example, CAFs induce Notch activation and conversely, induction of Notch3 by CAFs is associated with an increase in cancer stem cells in hepatocellular carcinoma." (PMID 33498866, 2021). "Previous data suggest that the expression of Notch3 is higher in tumor tissue than normal tissue in various solid tumors, including hepatocellular carcinoma, CRC, and gallbladder cancer." (PMID 41027955, 2025). "DLL4 was identified as ligand of Notch1 in hepatocellular carcinoma, Notch4 in glioblastoma and Notch3 in melanoma." (PMID 39951484, 2025). "For example, matrix metalloproteinase 28 (MMP28) enhances epithelial-mesenchymal transition (EMT) and promotes hepatocellular carcinoma metastasis via activating Notch3 Signaling." (PMID 37853162, 2023). "HIF-1α upregulated the expression of Notch1, Notch3 and Notch4 via binding to the hypoxia response elements in their promoter regions in hepatocellular carcinoma cell lines." (PMID 34988077, 2021). "The expression of aldehyde dehydrogenase (ALDH), a recognized CSC marker, is significantly positively correlated with Notch3 expression, as seen in OC, lung carcinoma (LC), hepatocellular carcinoma (HCC) and breast carcinoma (BC)." (PMID 34195229, 2021). "This review focuses mainly on the role of Notch3 signaling in hepatocellular carcinoma and its potential therapeutic applications against this malignancy." (PMID 28036048, 2016). "In parallel, we found that Notch3 attenuation resulted in the upregulation of β-catenin and the downregulation of Nanog in the hepatoma cell lines QGY7701 and HepG2." (PMID 25668819, 2015). "Notch3 exhibited higher expression levels in hepatoma cells compared with the immortalized normal liver cell line HL7702." (PMID 25668819, 2015). "The results add further support for the growing evidence of the usefulness of Notch3 as a therapeutic target for hepatocellular carcinoma." (PMID 25431954, 2014). "It has been reported that aberrant expression of Notch3 is found in many hepatocellular carcinoma cells, as frequently as that of Notch1." (PMID 21673954, 2011). "Moreover, Liu and colleagues reported that upregulated KDM1A expression in CAFs is a driver of Notch3-mediated cancer stem-like cells self-renewal in hepatocellular carcinoma." (PMID 34925656, 2021). "NOTCH3 down-regulation by siRNA decreased the expression of MMP-9 in the hepatocellular carcinoma." (PMID 31811815, 2019). "We also screened the Notch3 protein expression profiles in several hepatoma cell lines." (PMID 25668819, 2015). "With regard to therapeutic implications, Notch3-specific drugs could represent a valuable strategy to limit Notch signaling in the context of hepatocellular carcinoma over-expressing this receptor." (PMID 25431954, 2014). "Moreover, expression levels of SNORA74A and NOTCH3 are positively related with severity and poor prognosis of hepatocellular carcinoma (HCC) patients." (PMID 40270470, 2025). "Hepatocellular carcinoma tissues collected at Tottori University Hospital were used to determine the mRNA expression levels of CD44, NOTCH3, and GPX1." (PMID 30636370, 2019). "Emerging data have revealed aberrant Notch3 expression in hepatocellular carcinoma (HCC)." (PMID 25668819, 2015). "We confirmed in this study that Notch3 is potentially a specific marker of HCC and plays a role in the regulation of the CSCs in a hepatoma by interacting with the Wnt/β-catenin pathway." (PMID 25668819, 2015). "Among the hepatoma cell lines, we found that QGY7701 cells highly express Notch3." (PMID 25668819, 2015).
leukemia (23 papers, 2011 to 2025). A malignant (clonal) hematologic disorder, involving hematopoietic stem cells and characterized by the presence of primitive or atypical myeloid or lymphoid cells in the bone marrow and the blood. "On the other hand, when the signal dynamics model of leukemia T cells was set up, it was observed that Notch3 could activate NF-κB by associating with the pTα chain of the pre-T-cell receptor." (PMID 35463301, 2022). "Finally, HDAC6 silencing impaired leukemia outgrowth in mice, associated with reduction of Notch3 full-length protein in vivo." (PMID 29643474, 2018). "Here, we report that aberrant T cells from Notch3-dependent T-ALL participate in shaping the leukemia environment, through the control exerted on MDSCs." (PMID 35444651, 2022). "Mice were treated with intravenous injection of Juglone or vehicle alone (CTR) at days 21th and 23th after subcutaneous leukemia cells implantation and, on day 25th, excised tumors were evaluated for the effects on Notch3 and CHOP expression (, c)." (PMID 33071287, 2020). "We and others have previously suggested that epigenetic regulation at NOTCH3 gene locus promotes its aberrant gene expression in some cancers, including leukemia." (PMID 31001470, 2019). "We also show that CXCR4 surface expression is central to the migratory ability of CD4+CD8+ cells and such an expression is regulated by Notch3 through β-arrestin in human leukemia cells." (PMID 30038265, 2018). "Overall, our data suggest that in Notch3-induced T-ALL leukemia, high Notch3 and CXCR4 co-expression marks “pre-leukemic” DP thymocytes and allows their egression and propagation outside the thymus." (PMID 30038265, 2018). "De novo, we propose that hyperactive Notch3 signaling by boosting CXCR4-dependent migration promotes anomalous egression of CD4+CD8+ cells from the thymus in early leukemia stages." (PMID 30038265, 2018). "A role for NOTCH3 in leukaemia was reported in studies using transgenic mice overexpressing NOTCH3-ICD, which gave rise to T cell leukaemia." (PMID 25711903, 2015). "In their transgenic mouse model, Notch3 overexpression, specifically in T cells, led to the development of leukemia." (PMID 25538890, 2014). "A possible role of Notch3 in leukemia was postulated in studies in which transgenic mice expressing the constitutively active intracellular domain of Notch3 in thymocytes and T cells developed early and aggressive T-cell neoplasia." (PMID 22128846, 2011). "This enhancer is also regulated by NOTCH3 in NOTCH3-dependent leukemias." (PMID 35514954, 2022). "Altogether our results suggest that Notch3 inhibition may prevent leukemia cells from engaging a functional UPR needed to compensate the Juglone-mediated ER proteotoxic stress." (PMID 33071287, 2020). "Moreover, Pin1 deletion prevents leukemia progression by reducing Notch3 expression and blocking the expansion/invasiveness of circulating CD4+CD8+ T-cells in N3-ICtg blood." (PMID 30038265, 2018). "Similarly, the natural occurring phenolic compound juglone (5-hydroxy-1,4-naphthoquinone) had anti-Notch3 activities both in in vitro and in vivo leukemia settings, thus suggesting juglone-based therapies as potential approaches for the treatment of Notch3-dependent T-ALL." (PMID 34680255, 2021). "Notch3, JAG1, Hes2, Hes4 and Hes5 were frequently hypermethylated in B leukemia cell lines and primary B-ALL, in contrast to T-ALL cell lines and patient samples." (PMID 23637910, 2013). "In addition, the pre-TCR signal is important for Notch1/ICN1, Notch3- and TEL-JAK2-induced leukemias, indicating that developmental processes required for normal thymocyte development can be implicated in the pathogenesis of T-ALL." (PMID 35401501, 2022). "In keeping with these findings, in this work, we observed that Notch3 (but not Notch1) is able to interact with GRP78/Bip in leukemia cells in basal conditions." (PMID 33071287, 2020).
leukemia (continued). "Furthermore, we also observed that Juglone was able to induce Notch3 downmodulation and CHOP induction in vivo, finally exerting anti-leukemia growth in a human T-ALL xenograft mouse model." (PMID 33071287, 2020). "In general, expression of Hes5, Hes4 and Notch3 was restored in methylated leukemia cell lines treated by DAC with or without SAHA, a phenomenon associated with gene demethylation." (PMID 23637910, 2013). "More studies are needed to clarify how Notch 3 participates in hematological malignancy pathogenesis, while the lack of compelling data on Notch 4 possibly means a less direct or a non-canonical involvement in leukemia and lymphoma." (PMID 33374160, 2020). "Notch3 and Hes5 genes were predominantly expressed in primary T-ALL and some T cell lines but were silenced in majority of B cell leukemia and B cell lines, suggesting that Notch3 and Hes5 could be used as T cell lineage specific markers for leukemia diagnosis." (PMID 23637910, 2013). "Although NOTCH3 is assumed as a Notch1 target, machinery driving its transcription in T-ALL is undefined in leukemia subsets lacking Notch1 activation." (PMID 31001470, 2019). "Notch3, Hes5, Hes2, Hes4 and JAG1 genes were found frequently hypermethylated in various leukemia cell lines but not in normal controls." (PMID 23637910, 2013). "Methylation verification revealed that Notch3, Hes5, Hes2, Hes4 and JAG1 genes were frequently hypermethylated in various leukemia cell lines but not in normal controls." (PMID 23637910, 2013). "Notably, recent studies indicated epigenetic modifications at NOTCH3 gene locus to drive its expression in leukemia, as it has been demonstrated to be hypermethylated in B-ALL samples not expressing NOTCH3, while it has been found poorly or unmethylated in T-ALL context." (PMID 31001470, 2019).